KRAS (KRas proto-oncogene, GTPase)
Diseases named in the same sentence as KRAS in open-access papers (continued):
Sharing a sentence is not in itself a finding about the gene and the disease.
tumor (continued). "Moreover, we included normal and tumor organoids in which the oncogenic G12D mutation was introduced in the endogenous KRAS locus by CRISPR-Cas9-induced homologous recombination." (PMID 27845624, 2016). "Of the tumor cases examined, 87 (45.5%) had wild type KRAS and 104 (54.5%) had KRAS mutations." (PMID 26991109, 2016). "However, we do note that we also observed the KRAS selective effect of CDK1 inhibition in tumour cell lines with naturally occurring KRAS mutations." (PMID 26881434, 2016). "Interestingly, KRAS oncogenic mutations was the most frequent molecular abnormalities in this type of tumor and occurs in more than 90% of PDAC." (PMID 26646588, 2016). "These tumours tend to feature KRAS mutations more frequently than CIMP tumours." (PMID 27279102, 2016). "Both studies found KRAS to be mutated more often in right-sided tumor than in left-sided." (PMID 27037031, 2016). "The first group is patients with tumours harbouring the KRAS exon 2 G13D mutation, who in retrospective series (with small numbers only) appear to respond to EGFR-I (in trials before KRAS selection became an eligibility criteria), but are currently precluded from accessing such treatment." (PMID 27246726, 2016). "BRAF D594N is a kinase-dead protein; nevertheless, considering results in mice co-occurrence of BRAF D594N and KRAS mutations might contribute to tumor progression." (PMID 27095580, 2016). "Four studies assessed KRAS mutation in plasma DNA and the others in tumor specimens." (PMID 26840022, 2016). "For example, KRAS mutations were found in 8/22 tumor samples (36.4%)." (PMID 27448974, 2016). "Additionally, prospective results concerning concordance of the KRAS mutation status in pre- and post-therapeutic tumor samples (referred to as intertumoral heterogeneity) are rare and of conflicting nature." (PMID 27064574, 2016). "The lower sensitivity for KRAS mutation as compared with EGFR mutations could be due to the different tumor load." (PMID 27448974, 2016). "To this end we examined whether the presence of different KRAS substitution within tumors showed an association with higher tumor stage." (PMID 26902163, 2016). "The ORR was higher in patients with KRAS exon 2 wild-type tumours (87.5%, 95% CI 61.7–98.4) compared with those with KRAS exon 2 mutated tumours (55.6%, 95% CI 21.2–86.3), with all four complete responses reported in the study occurring in patients with KRAS exon 2 wild-type tumours." (PMID 26766738, 2016). "In explant cells derived from these PDX tumor models with a KRAS G12R mutation, treatment with inhibitors of CDKs (including CDK9) reduced phosphorylation of a marker of CDK9 activity (phospho-RNAPII CTD Ser2/5) and reduced viability/growth of explant cells derived from PDAC PDX models." (PMID 26934555, 2016). "This established that the KRAS/CDK1 synthetic lethality applies in tumour cells with either amino acid position 12 (p.G12V, pG12D, p.G12S) or amino acid position 13 (p.G13D) KRAS mutations and can also be replicated in vivo in a xenograft model using a small molecule CDK1 inhibitor." (PMID 26881434, 2016). "Somatic mutation analyses of FLCN, EGFR, and KRAS were also done in microdissected neoplasms." (PMID 26974543, 2016). "Thus, when Bcl-XL was inhibited to bind and repress Bim, in conjunction with direct MEK inhibition, it led to significant apoptosis in many KRAS mutant cell lines from varying origins and caused tumor regression." (PMID 28025559, 2016).
tumor (continued). "Next generation sequencing of her tumor revealed a G12V mutation in KRAS." (PMID 27231576, 2016). "Of note, one tumor had two KRAS mutations (c.35G>A Gly12Asp; c.38G>A Gly13Asp)." (PMID 27999344, 2016). "In general, KRAS mutation status is assessed by analyzing primary tumor tissue." (PMID 27064574, 2016). "In all subgroup analyses (age, using a cut-off of 65 years, ECOG performance status, gender, and tumor KRAS mutational status) the use of antiangiogenic drugs beyond progression improved PFS with comparable hazard ratios in both dichotomized groups, respectively." (PMID 27656206, 2016). "Furthermore, mutation in the KRAS oncogene, which has been regarded as generally infrequent in microsatellite-unstable tumours, was clearly associated with Type A MSI." (PMID 26298837, 2016). "KRAS mutations were present in only 4% of the tumours and all tumours were EGFR wild-type." (PMID 26844548, 2016). "This allowed us to identify which of the KRAS driver substitutions within codons 12 and 13 are relatively over- and which are relatively under-represented, given mutational biases in the different tumor types." (PMID 26902163, 2016). "Therefore, in addition to the inactivation of Apc, activation of ERK signaling, either by the activation of SHP-2 as demonstrated herein or by mutation of KRAS, appears to act synergistically resulting in increased tumor multiplicity in the intestine." (PMID 27582544, 2016). "Analyses of EGFR and KRAS mutations were successfully performed in 170/174 (97.7%) primary tumours." (PMID 26844548, 2016). "The frequency of KRAS mutation shows a large variation among the tumor types." (PMID 27032374, 2016). "Mutations in the KRAS oncogene were initially regarded as infrequent in MSI+ tumours." (PMID 26298837, 2016). "We therefore next turned to examining whether the presence of KRAS substitutions we predict to be less or more favored within the various tumor types associated with clinical parameters according to external studies." (PMID 26902163, 2016). "Some of them suggested that tumor specific mutations such as KRAS or EGFR presented in cfDNA might be useful prognostic and predictive biomarkers for NSCLC." (PMID 27323821, 2016). "The frequencies of the most predominant mutation types reported for PDAC in ICGC, i.e p.G12D, p.G12V, p.G12R, p.G12C followed by p.Q61H, p.Q61R and p.Q61L paralleled the frequencies of the cfDNA KRAS mutations in cases reflecting the probable tumor origin of the cfDNA KRAS mutations." (PMID 27705932, 2016). "Interestingly, in our series 3/4 EGFR mutant patients with progressive disease after EGFR TKI treatment had coexisting mutations in KRAS or BRAF in the primary tumor, in two cases at an allelic frequency higher than EGFR mutations." (PMID 27448974, 2016). "PDAC has the highest incidence of KRAS mutation of all types of tumours, and more than 50% of patients could exhibit this abnormality; additionally, the KRAS mutation is considered a critical event for the initiation of this type of cancer." (PMID 27689078, 2016). "The frequency for KRAS mutations in MSI+ tumours has been controversial." (PMID 26298837, 2016). "This variability of KRAS mutational status may reflect the fact that it behaves as a “passenger” mutation that, by definition, barely influences tumor outcome." (PMID 26968843, 2016). "All of these genes have been associated with tumor growth and progression, and recent studies suggest that additional mutations in KRAS and NRAS, as well as downstream mutations in BRAF or PIK3CA, may cause resistance to anti-EGFR treatment." (PMID 26989027, 2016).
tumor (continued). "It has been reported that tumours harbouring a G13D mutation in the KRAS gene might be sensitive to EGFR-inhibitors." (PMID 26386973, 2015). "We next asked whether the presence of a mutant KRAS allele is associated with NRF2 activation in human tumor cell lines." (PMID 26301506, 2015). "Thus it would be ideal to use this in combination with tumor specific DNA mutation detection, such as mutant KRAS, which is the most common genetic alteration found in PDAC occurring in approximately 90 % of tumors." (PMID 26498594, 2015). "However, this ability of Flag-KRAS to rescue the poor tumor growth of KRAS-knockdown cells was lost if the C118S mutation was introduced into KRAS." (PMID 25902334, 2015). "Consequently, we evaluated the prespecified tumor subtypes with respect to clinicopathologic features in biomarker combinations of KRAS mutations and MMR status." (PMID 26042813, 2015). "In addition, we performed multivariate Cox regression combining MACC1 expression level with the tumor characteristics KRAS G12 or G13 mutation, BRAF V600 mutation and MSI status." (PMID 25742883, 2015). "However, we observed that patients presenting with synchronous metastases were more likely to have a tumor with KRAS mutation (p = 0.049)." (PMID 25888291, 2015). "Tumors with BRAF or KRAS mutations were in correlation with elevated serum level of tumor biomarkers of CRC and the combination of serum biomarkers and molecular mutation status may enhance the more precise risk stratification of CRC patients." (PMID 26530529, 2015). "Although numerous advances in understanding the molecular biology of pancreatic cancer and in diagnosis and treatment regarding KRAS mutations, tumor metabolism, and tumor immunology have been made, minimal progress has been achieved in improving the survival of patients." (PMID 25654224, 2015). "Given that the restoration of tumor suppressive miRNAs is a relatively safe, effective strategy for cancer treatment, systemic or focal administration of miR-4689 represents a novel therapeutic strategy for treating mutated KRAS cancers." (PMID 25756961, 2015). "An additional step of stratification and treatment of LKB1-deficient tumours may be to group them with co-mutations that frequently arise in genes such as KRAS and BRG1." (PMID 26196184, 2015). "The same trend for dissemination can be seen for BRAF wild type tumours with a KRAS mutation." (PMID 25884297, 2015). "Many factors could affect mutation cfDNA analysis, including both presence of tumor clonal heterogeneity and strict compartmentalization of KRAS mutation profile." (PMID 25946211, 2015). "By blocking the mevalonate pathway in CRC patients with KRAS mutated tumours, the activated KRAS pathway might be inhibited." (PMID 26386973, 2015). "In patients who do not respond to this therapy, it has been demonstrated that the tumour cells carried one of the mutations of the KRAS gene, which is found located on the EGFR gene pathway, which caused the activation of this pathway independently of the EGFR blocking." (PMID 25932044, 2015). "Tumour-specific KRAS mutations were detected in a total of 119 plasma samples." (PMID 25875772, 2015). "As for OS, we could not find any statistical difference among patients with tumor harboring the three more common KRAS mutations, separately analyzed, and those with wild-type tumor." (PMID 26416458, 2015). "In the case of doubts of KRAS status in the primary tumor, tests of KRAS mutations in metastatic tissue could be useful, but this can be limited by obtaining patients’ cancer tissues." (PMID 25628770, 2015). "For KRAS codons 12 and 13 mutations in 29 metastatic CRCs, 83.3% sensitivity, 86.9% specificity and 86.2% accuracy were revealed between cfDNA and direct DNA sequencing of tumor FFPE specimens." (PMID 26452027, 2015). "Importantly, the PIK3CA mutations and BRAF mutations, occurring in cases with wild-type KRAS, are known to be mechanistically activating and are enriched in other tumour types." (PMID 25855536, 2015).
tumor (continued). "KRAS mutated tumours were more commonly seen in patients with disseminated disease." (PMID 25884297, 2015). "This single-arm, phase II study was designed to test the safety and efficacy of the addition of simvastatin to cetuximab in patients with a KRAS mutation in their tumour who were previously treated with fluoropyrimidine, oxaliplatin and irinotecan based regimens." (PMID 26386973, 2015). "Interestingly, one tumor sample harbored two different KRAS mutations (p.G13D and p.Q61R) whilst another tumor was KRAS/BRAF double mutant." (PMID 25568935, 2015). "However, we were able to obtain sufficient DNA from 12 of the 31 patients tested for a KRAS mutation in plasma in order to confirm the presence of the same mutation in the primary tumor." (PMID 26498594, 2015). "The five metastatic tumours with KRAS mutations ‘loss' were first confirmed as genetically identical with the corresponding primary tumours, by comparing both the pre-sequencing mass spectrometric fingerprint genotyping and the genome-wide SNPs called from sequencing data." (PMID 26647728, 2015). "Direct sequencing yielded 4 discordant results; however, re-evaluation of mutation status using a combination of the ARMS method and enrichment of tumour cells by laser capture microdissection found identical KRAS mutations in all 19 matched pairs (100 % concordance)." (PMID 26338018, 2015). "Tumor cell enrichment correlated significantly with the abundance of KRAS-mutated DNA." (PMID 26220423, 2015). "The presence of KRAS mutation microheterogeneity in many tumours which are KRAS wild-type by standard sequencing technologies together with the absence of KRAS mutational macroheterogeneity further indicated that these new subclones rarely undergo significant clonal expansion." (PMID 25555261, 2015). "Approximately 30–50% of CRC tumours have a mutated KRAS gene, which indicates that up to 50% of the patients with this type of cancer could respond to therapy with antireceptor antibodies against the epidermal growth factor, EGFR." (PMID 25932044, 2015). "In addition, we aimed to validate the prognostic value of the pre-treatment levels of cfDNA and analyse the tumour-specific KRAS mutations in the plasma." (PMID 25875772, 2015). "We have shown that the dual activation of the PI3K and Ras/MAPK pathways, via PTEN loss and KRAS activation, is sufficient to promote robust tumor growth and thus, have developed a novel model system for elucidation of potential crosstalk and novel feedback mechanisms." (PMID 26497685, 2015). "Wild-type Ras proteins may even promote more malignant stages of tumorigenesis, as shRNA-mediated knock down of wild-type Ras proteins has been shown to inhibit the tumor growth of KRAS mutation-positive cancer cell lines isolated from late stage disease." (PMID 26452271, 2015). "Although the direct mechanism by which dormancy occurs is beyond the scope of this study, it is plausible that the loss of PTEN and KRAS activation could act as potential drivers of clinical tumor dormancy." (PMID 26497685, 2015). "On this basis, we hypothesized that a different KRAS mutational status in NSCLC patients determines a different profile in the tumor response to treatments." (PMID 26353932, 2015). "Recent studies have revealed that oncogenic KRas mutations reprogram tumor cells to states dependent on enhanced glucose and glutamine metabolism, which are required to support the upregulated antioxidant capacity needed for tumor growth." (PMID 26097885, 2015). "This led to the question whether increased activation of KRAS signaling by KRAS mutations can be modulated, thereby making KRAS mutated tumours sensitive to EGFR inhibitor therapy." (PMID 26386973, 2015). "Notably, we observed significantly lower frequency or even loss of KRAS mutation in the metastatic tumours as compared with their paired primary tumours." (PMID 26647728, 2015).
tumor (continued). "These events may include mutations in key genes that when estimated as % of the tumor population emerge as subclonal events in different MM patients: KRAS (20–72%), NRAS (32–96%), BRAF (36–92%) or DIS3 genes (29–81%)." (PMID 25929340, 2015). "Furthermore, targeting CDK4 alleles in advanced tumours of this KRAS-mutant model induced senescence and prevented tumour progression, thereby highlighting the pharmacological importance of CDK4 for therapeutic strategies." (PMID 25625291, 2015). "GSEA further showed that our murine Stat3-deficient KrasG12D tumours strongly correlate with a gene expression signature associated with human KRAS mutant lung tumours, and importantly, also with a poor prognosis-gene signature—more than Stat3-proficient KrasG12D tumours." (PMID 25734337, 2015). "Additionally, the novel finding is that PTEN loss or KRAS activation individually is sufficient to promote cellular persistence reminiscent of tumor cell dormancy, has potential implication for cancer dormancy and reoccurrence risk." (PMID 26497685, 2015). "Although the mutation status of EGFR and KRAS are used as predicting biomarkers for EGFR targeted therapy in other tumor types, their (extremely) low prevalence in HNSCC will likely preclude a major role in helping to define treatment options in these patients." (PMID 24899223, 2014). "KRAS mutations in both tumor tissue and plasma are a strong prognostic marker for poor outcomes." (PMID 25491325, 2014). "KRAS mutation status in primary tumor and corresponding CTC-enriched samples in mCRC patients." (PMID 25137394, 2014). "In addition, the MAP kinase pathway is already engaged due to the KRAS or BRAF mutations in the tumor cell lines used in this work." (PMID 25285080, 2014). "In particular KRAS was the most frequently mutated gene in the 153 tumours (28.1%)." (PMID 24867389, 2014). "The current findings support the rationale for using the CTCs as a dynamic source of tumor cells which, by re-evaluating their KRAS mutation status, could predict, perhaps more accurately, the response of mCRC patients to targeted therapy." (PMID 25137394, 2014). "In addition, loss of the main NF-κB subunit p65 in KRAS-lung tumors was associated with a reduction in tumor number, spread and grade." (PMID 24955217, 2014). "KRAS mutation was detected in tumor tissue of the male patient." (PMID 24782938, 2014). "Our analysis showed that KRAS mutation by specific amino acid substitution varies by tumor type." (PMID 25313136, 2014). "We retrospectively investigated 6 cases of this very rare neoplasm in order to investigate the mutational status of KRAS, EGFR, PDGFR-α and KIT, as well as the immunohistochemical expression pattern of CD117, EGFR and COX-2, and possibly find new therapeutic targets." (PMID 24934485, 2014). "If KRAS status was taken into account, in accordance to OS, a significant difference in PFS associated with primary tumor location was only evident in patients with KRAS codon 12/13 wild-type tumors (4.6 vs. 8.4 months, p = 0.007, HR = 0.54), but not in patients presenting a mutation in these loci." (PMID 24816724, 2014). "To date, therapy decisions rely mainly on KRAS mutation status of the primary tumor; however, genetic changes occurring during disease progression and acquired resistance to treatment may alter tumor's biology." (PMID 25137394, 2014). "Therefore, miR-200c targeting KRAS is of great interest in order to understand and predict tumor progression and therapy susceptibility of cancer patients." (PMID 24368337, 2014).